GPIHBP1 (glycosylphosphatidylinositol anchored high density lipoprotein binding protein 1)
Diseases named in the same sentence as GPIHBP1 in open-access papers (continued):
Sharing a sentence is not in itself a finding about the gene and the disease.
Insulin resistance (3 papers, 2012 to 2025). Increased resistance towards insulin, that is, diminished effectiveness of insulin in reducing blood glucose levels. "To elucidate the mechanism underlying impaired TG homeostasis in insulin resistance state we studied the effect of insulin on GPIHBP1 protein expression in human microvascular endothelial cells (HMVEC) under flow conditions." (PMID 30408040, 2018). "Circulating GPIHBP1 levels are affected in a compensatory manner in response to a decrease in circulating LPL levels correlated with insulin resistance." (PMID 40507147, 2025). "Second, the study-design precludes examination of causality for the relationship between insulin resistance and LPL, HTGL, and GPIHBP1." (PMID 40507147, 2025). "Very little is known about the regulation of GPIHBP1 in the setting of metabolic abnormalities including the presence of insulin resistance." (PMID 30408040, 2018). "Thus, to further understand the mechanism underlying the hyperTG phenotype we evaluated adipose tissue GPIHBP1 expression in a T2DM mouse model as well as in subjects with ranging levels of insulin resistance." (PMID 30408040, 2018). "We thus asked the question whether insulin resistance may influence the formation of dimer/multimer GPIHBP1 which ultimately leads to reduced lipolytic capacity in adipose tissue." (PMID 30408040, 2018). "An increased GPIHBP1 level might compensate for decreased LPL levels due to insulin resistance." (PMID 40507147, 2025). "However, it is currently known whether GPIHBP1 expression in adipose tissue is differentially expressed in an insulin resistance state." (PMID 30408040, 2018). "To identify such mechanisms, we analyzed LPL, GPIHBP1, HTGL and insulin resistance in middle-aged Japanese individuals." (PMID 40507147, 2025). "This study showed that reciprocal fluctuations in LPL, GPIHBP1, and HTGL levels in the peripheral bloodstream are correlated with insulin resistance." (PMID 40507147, 2025). "A high insulin resistance affected circulating levels of LPL and GPIHBP1 in the statin-treated groups." (PMID 40507147, 2025). "The correlation between reciprocal fluctuations in LPL, GPIHBP1, and HTGL and insulin resistance was evident under physiological conditions and was attenuated in IFG." (PMID 40507147, 2025). "In old, obese rats that showed signs of insulin resistance, the responses of ANGPTL4 and GPIHBP1 mRNA and of LPL activity were severely blunted (at 26 weeks of age) or almost abolished (at 52 weeks of age)." (PMID 23176178, 2012). "Further, circulating GPIHBP1 levels may be affected by renal function and in a compensatory manner in response to a decrease in circulating LPL levels correlated with insulin resistance." (PMID 40507147, 2025). "The positive correlation between circulating levels of HTGL and GPIHBP1 could be explained by an increase in GPIHBP1 levels, which may compensate for the decrease in LPL levels attributed to increased insulin resistance." (PMID 40507147, 2025). "The current study demonstrates that visceral adipose tissue GPIHBP1 protein concentration (rather than gene expression) in visceral adipose tissue is affected in a chow-fed murine model of insulin resistance, the Leprdb/db mice." (PMID 30408040, 2018).
endothelial dysfunction (2 papers, 2025). In vascular diseases, endothelial dysfunction is a systemic pathological state of the endothelium (the inner lining of blood vessels) and can be broadly defined as an imbalance between vasodilating and vasoconstricting substances produced by (or acting on) the endothelium. "GPIHBP1 is localised to endothelial cells, and fetoplacental endothelial dysfunction could be related to its expression and possibly to its levels in the circulation." (PMID 41142641, 2025). "Thus, in the cluster of malignant, we speculated that the high expression of Cd36, Lpl, Gpihbp1, Fabp4, and Pparg was important in the metabolism of FAs and may contribute to endothelial dysfunction." (PMID 40440080, 2025).
familial chylomicronemia (2 papers, 2014 to 2024). "Familial LPL deficiency is a rare autosomal recessive disorder which is characterized by primary hyperchylomicronemia due to homozygous or compound heterozygous mutations of LPL gene as well as to homozygous mutations of APOC2,GPIHBP1, APOA5 or LMF1 genes." (PMID 24788417, 2014).
autoimmune disease (1 paper, 2025). A disorder resulting from loss of function or tissue destruction of an organ or multiple organs, arising from humoral or cellular immune responses of the individual to their own tissue constituents. "An interesting question remains regarding the relationship between GPIHBP1-AAS and autoimmune disease with identifiable genetic underpinnings." (PMID 40816829, 2025). "A larger exploration of this relationship between GPIHBP1-AAS and autoimmune disease could be a focus of future investigation." (PMID 40816829, 2025).
Autoimmunity (1 paper, 2025). The occurrence of an immune reaction against the organism's own cells or tissues. "As reported by Strøm, one of our patients adds a new form of autoimmunity to STAT1 GOF, namely autoimmune hypertriglyceridemia due to GPIHBP1 autoantibodies." (PMID 40881691, 2025).
diabetic polyneuropathy (1 paper, 2026). "After adjustment for confounders, including estimated glomerular filtration rate (eGFR), the association between GPIHBP1 and diabetic neuropathy remained statistically significant although attenuated." (PMID 42194055, 2026).
hyperlipoproteinemia (1 paper, 2022). An elevated concentration of lipoproteins. "Moreover, in the systematic review, we present 62 patients with pathogenic variants in the GPIHBP1 gene and clinical findings, associated with hyperlipoproteinemia." (PMID 36051701, 2022).
renal carcinoma (1 paper, 2019). A carcinoma arising from the epithelium of the renal parenchyma or the renal pelvis. "GPIHBP1:GPIHBP1 RNA and protein is increased in renal cancer." (PMID 31068932, 2019).
sarcopenia (1 paper, 2019). Progressive decline in muscle mass due to aging which results in decreased functional capacity of muscles. "However, the relationship between LPL and GPIHBP1 and skeletal muscle mass, including sarcopenia, has not been fully understood." (PMID 30947712, 2019).
type 5 hyperlipoproteinemia (1 paper, 2007). "The association of this coding sequence variant with severe type 5 hyperlipoproteinemia with chylomicronemia, its absence from normolipidemic subjects together with other evidence for its likely pathogenicity appears to link the GPIHBP1 gene with severe human metabolic phenotypes." (PMID 17883852, 2007).
cancer (4 papers, 2009 to 2020). A tumor composed of atypical neoplastic, often pleomorphic cells that invade other tissues. "PLAG forms vesicles in cell culture media and a major component of the micelle membrane, which is captured by GPIHBP1, a vesicle-capturing ligand of cancer cells." (PMID 32121107, 2020). "Of the 201 downregulated genes, 125 were identified in the previous study (GEO results) and only 76, such as cysteine rich domain 2 (STAC2), BTNL9, CA4, GPIHBP1 and PIGR, had not been studied on any cancer." (PMID 31182966, 2019).
tumor (2 papers, 2019 to 2025). "Experiments using an EC xenograft model demonstrated that the oncogenic role of KLF13 was mediated through regulation of GPIHBP1, as tumor size, tumor volume and tumor weight were all greatly reduced in KLF13 + shGPIHBP1 group relative to those in KLF13 group." (PMID 40450000, 2025). "This table details the tumor diagnosis, location, 1p/19q co-deletion, and IDH1 mutation status, as well as the presence of GPIHBP1." (PMID 31169500, 2019). "IHC staining of tumor tissues showed that KLF13 and GPIHBP1 expression were increased in KLF13 overexpressing mice, while they were decreased in mice with GPIHBP1 knocked down." (PMID 40450000, 2025). "IHC results showed a positive relation between the expression of GPIHBP1 and KLF13 in tumor samples." (PMID 40450000, 2025).
vascular disorder (1 paper, 2025). A general term used to describe any disease affecting blood vessels]. "Comparable results were reported in a study that investigated the association between vascular disorders and circulating GPIHBP1 levels." (PMID 41142641, 2025).
GPIHBP1 also shares sentences with these, for which no sentence is quoted: Obesity (6 papers); systemic lupus erythematosus (4); dyslipidemia (3); gestational diabetes mellitus (2); Nephropathy (2); antibody deficiency against (1); antiphospholipid syndrome (1); carbohydrate metabolism disorders (1); cholesterol ester storage disease (1); chronic renal failure (1); coronary artery disease (1); diabetic kidney disease (1); diabetic retinopathy (1); esophageal cancer (1); glioblastoma (1); Hashimoto disease (1); heart failure (1); Hepatic steatosis (1); Hyperglycemia (1); hyperlipoproteinemia type 1D (1); Infertility (1); membranous nephropathy (1); Mendelian diseases (1); metabolic disorder (1); mucous membrane pemphigoid (1); multiple sclerosis (1); Palmoplantar keratoderma (1); rheumatoid arthritis (1); Splenomegaly (1); steatosis (1).
A further 2 diseases each share a sentence with GPIHBP1 in 1 paper.